BRCA2 (BRCA2 DNA repair associated)
Diseases named in the same sentence as BRCA2 in open-access papers (continued):
Sharing a sentence is not in itself a finding about the gene and the disease.
ovarian carcinoma (continued). "By pooling the outcomes of 18,396 ovarian cancer patients from 34 individual studies, we found that BRCA mutation (BRCA1/2, BRCA1 and BRCA2) carriers had significantly improved OS and PFS benefits in ovarian cancer patients." (PMID 27690218, 2017). "Overall, approximately 5%–10% of breast and ovarian cancer cases are due to mutations in the high-penetrance genes BRCA1 and BRCA2 (BRCA)." (PMID 28157161, 2017). "According to the NCCN Ovarian Cancer Guideline Version 1.2016, BRCA1 or BRCA2 mutations are high risk carriers of ovarian cancer." (PMID 29088888, 2017). "Advances in the understanding of the molecular biology of epithelial ovarian cancer, and the impact of BRCA1 and BRCA2 gene mutations on cellular DNA repair pathways, has led to the development of PARP inhibitors, an exciting new class of targeted therapy." (PMID 28665051, 2017). "Earlier studies investigating the effect of PRS on the absolute risks of breast and ovarian cancer risks of BRCA1 and BRCA2 mutation carriers demonstrated potential for risk stratification." (PMID 28376175, 2017). "This property has been successfully translated into the clinic for breast and ovarian cancer patients with mutations in the tumor suppressor genes, BRCA1 or BRCA2." (PMID 26910887, 2016). "We examined the entire coding sequences of the BRCA1 and BRCA2 genes and genotyped a recurrent mutation of the PALB2 gene (c.509_510delGA) in 121 women with familial and/or early-onset breast or ovarian cancer from Southern Poland." (PMID 26843898, 2016). "About 10% of all breast and ovarian cancers are dominantly inherited mainly by mutations in the BRCA1 and BRCA2 genes." (PMID 27974137, 2016). "The risk of ovarian carcinoma at 70 years old was reported as 39% and 11% with BRCA1 and BRCA2 mutation, respectively." (PMID 27643881, 2016). "In a study of 200 Polish families with three or more breast or ovarian cancers a BRCA1/2 mutation was identified in 64 %; the prevalence of BRCA1 mutations was 60 % and the prevalence of BRCA2 mutations was 4 %." (PMID 26843898, 2016). "The 9p22 locus was first found to be associated with ovarian cancer risk in the general population, and subsequently to be an ovarian cancer risk modifier in BRCA1 and BRCA2 mutation carriers." (PMID 27463617, 2016). "Mutations in HR genes such as BRCA1, BRCA2, or RAD51C predispose individuals to breast and ovarian cancers." (PMID 26748828, 2016). "Mutations in DNA damage response factors BRCA1 and BRCA2 confer sensitivity to poly(ADP-ribose) polymerase (PARP) inhibitors in breast and ovarian cancers." (PMID 27613518, 2016). "We report a comprehensive analysis of the prevalence of BRCA1 and BRCA2 germline mutations in Pakistani patients with TNBC and non-TNBC selected for age of onset or family history of breast/ovarian cancer." (PMID 27553291, 2016). "Among 71 Jewish patients with ovarian cancer, 22 had BRCA1 three germline mutations and one truncating mutation, and 12 had BRCA2 truncating mutations vs 37 patients with sporadic ovarian cancer." (PMID 26753012, 2016). "The ovarian cancers that predominantly develop in BRCA1 and BRCA2 mutation-carriers are of serous or endometrioid histology and of high grade." (PMID 27468354, 2016). "We screened 121 women with familial and/or early-onset breast or ovarian cancer for mutations in BRCA1, BRCA2 and PALB2." (PMID 26843898, 2016). "The most important genes in the context of genetic counseling for ovarian cancer susceptibility are BRCA1 and BRCA2, which account for approximately 24% of the familial risk among first-degree relatives." (PMID 27463617, 2016). "One example is the upregulation of EMSY, a putative oncogene that transcriptionally silences exon 3 of BRCA2 that links the BRCA2 pathway to sporadic breast and ovarian cancer." (PMID 27642590, 2016). "In this study, we screened the entire coding regions and exon-intron boundaries of the BRCA1 and BRCA2 genes in 133 familial breast/ovarian cancer patients from eastern China." (PMID 26852015, 2016).
ovarian carcinoma (continued). "The median age at diagnosis of the 5 BRCA2-positive patients was 72.0 [62.0–72.5] years, and 2 had a positive first-degree family history of breast and/or ovarian cancer." (PMID 27377827, 2016). "Population-based genome wide association studies have identified a locus at 9p22.2 associated with ovarian cancer risk, which also modifies ovarian cancer risk in BRCA1 and BRCA2 mutation carriers." (PMID 27463617, 2016). "Identifying more strongly associated variants with ovarian cancer in the 9p22.2 region relative to the initial GWAS hit in BRCA1 and BRCA2 mutation carriers will refine the cancer risks associated with this locus further." (PMID 27463617, 2016). "Whilst PARP inhibitors have shown clinical utility in BRCA1/BRCA2 mutant breast and ovarian cancers, the story is much less clear in the majority of TNBCs, where surrogate markers of BRCA1 deficiency have not yet been identified." (PMID 27487152, 2016). "To evaluate the effects of BRCA2 ASO and olaparib on population dynamics and resistance to treatment over time, we devised a co-culture model of SKOV-3 ovarian cancer cells stably expressing either shRNA targeting BRCA2 or control shRNA." (PMID 26959114, 2016). "Friedenson has summarized these reports, analyzing data from more than 30 epidemiological studies on the incidence of other than the breast or ovarian cancers in BRCA1 and BRCA2 mutation carriers and in large populations eligible for mutation testing." (PMID 26779294, 2016). "Associations between selected SNPs from 9p22.2 and ovarian cancer in BRCA1, BRCA2 and combined analysis of BRCA1/2 mutation carriers." (PMID 27463617, 2016). "The lifetime risk of developing ovarian cancer is 40–60 and 11–27% for BRCA1 and BRCA2 mutation carriers, respectively." (PMID 27242959, 2016). "A total of 133 unrelated patients with personal and family histories of breast and/or ovarian cancer underwent BRCA1 and BRCA2 germline mutation screening." (PMID 26852015, 2016). "Several studies have focused on clinical and pathological features of breast and ovarian cancer associated with BRCA1 and BRCA2 mutations." (PMID 27129401, 2016). "Mutations in the BRCA1, BRCA2 and PALB2 genes are well-established risk factors for the development of breast and/or ovarian cancer." (PMID 26843898, 2016). "We comprehensively characterized the associations of genetic variants in the region with ovarian cancer risk for BRCA1 and BRCA2 mutation carriers." (PMID 27463617, 2016). "BRCA1/BRCA2 mutations are often found in hereditary breast and ovarian cancers, while somatic mutations of BRCA1/BRCA2 are rare in sporadic breast and ovarian cancers." (PMID 26967246, 2016). "Pathogenic mutations in BRCA genes were found in 13 of the 47 (28%) ovarian cancers: eight were in BRCA1 and five in BRCA2." (PMID 26745875, 2016). "Genotype data were available for 15,252 (2,462 ovarian cancer cases) BRCA1 and 8,211 (631 ovarian cancer cases) BRCA2 mutation carriers." (PMID 27463617, 2016). "BRCA1 and BRCA2 germline mutations are the most frequent HBOC signatures, and they increase the lifetime risk of developing breast and ovarian cancers by as much as 80%." (PMID 28009814, 2016). "In young women identified with a BRCA1 or BRCA2 mutation, RRS is performed in an effort to reduce ovarian cancer risk while maintaining adequate hormonal levels to avoid the effects of early menopause." (PMID 27200296, 2016). "Poly (ADP-ribose) polymerase (PARP) inhibitor (PARPi) olaparib has been approved for treatment of advanced ovarian cancer associated with BRCA1 and BRCA2 mutations." (PMID 27498558, 2016). "Early phase clinical trials with PARPi have been promising in patients with advanced BRCA1 or BRCA2-associated breast, ovary and prostate cancer and have led to limited approval for treatment of BRCA-deficient ovary cancer." (PMID 27428646, 2016).
ovarian carcinoma (continued). "In this study, we determined the sequence of BRCA1 and BRCA2 in 135 breast and/or ovarian cancer patients by NGS, which was then validated using Sanger sequencing." (PMID 25802882, 2015). "For example, women carrying highly penetrant mutations in the BRCA1 and BRCA2 genes have an elevated risk of developing breast (BRCA1/2 carriers, 36–90%) and ovarian cancer (BRCA1 carriers, 24–59%; BRCA2 carriers, 8–35%)." (PMID 26325576, 2015). "Inactivating mutations in the BRCA1 (MIM 113705) and BRCA2 (MIM 600185) genes confer a high risk of developing breast and ovarian cancer." (PMID 25683334, 2015). "In conclusion, the current standard RRSO at age 35–40 (BRCA1) or 40–45 (BRCA2) is highly effective in reducing ovarian cancer incidence." (PMID 26286255, 2015). "Although genetic testing for BRCA1 and BRCA2 for women with ovarian cancer is available in the neighbouring province of Ontario, referrals for genetic testing of ovarian cancer patients is on an ad hoc basis in Quebec." (PMID 25884701, 2015). "Ovarian cancer patients carrying alterations (i.e., germline mutations, somatic mutations, hypermethylations and/or deletions) of BRCA1 or BRCA2 (BRCA1/2) have a better prognosis than BRCA1/2 alteration non-carriers." (PMID 25537514, 2015). "Oral Contraceptives: The use of oral contraceptives has demonstrated a reduction in the risk of ovarian cancer by up to 45% to 50% in BRCA1-mutation carriers and up to 60% in BRCA2-mutation carriers." (PMID 26557407, 2015). "The study of BRCA1 and BRCA2 genes and their alterations has been essential to the understanding of the development of familial breast and ovarian cancers." (PMID 25683334, 2015). "Large rearrangements in BRCA1 and BRCA2 occur in a small percentage (<1%) of patients tested for hereditary breast and ovarian cancer." (PMID 25632310, 2015). "The aim of this study was to detect BRCA1/BRCA2 aberrant transcripts resulting from alternative splicing, in women with a known family history and/or early onset of breast and/or ovarian cancer, tested wild-type for BRCA1 and BRCA2." (PMID 25683334, 2015). "Some of these such as IDH1 mutations in glioblastoma are widely known; for others such as BRCA2 and NCOA3 mutations in ovarian cancer there is some evidence in the literature; while the remaining are genuinely novel." (PMID 25950620, 2015). "Genetic testing for BRCA1 and BRCA2 provides valuable information for determining the clinical management of patients with breast/ovarian cancer." (PMID 25683334, 2015). "In the group of 134 patients with unselected primary ovarian cancer, pathogenic BRCA1 or BRCA2 mutations were found in 20 individuals (14.9 %)." (PMID 25366421, 2015). "A previous study of French Canadian women with ovarian cancer was limited by both sample size investigated, and by spectrum of BRCA1 and BRCA2 mutations screened, where additional mutations have since been identified and found to recur in this population." (PMID 25884701, 2015). "At least 5 of the 17 known FA genes, D1/BRCA2, J/BRIP1, N/PALB2, O/RAD51C and S/BRCA1, are well-established breast and/or ovarian cancer susceptibility genes." (PMID 26085575, 2015). "Germline and somatic mutations in BRCA2 (and BRCA1) have been associated with survival in two ovarian cancer studies." (PMID 25950620, 2015). "We compare the standard strategy to reduce ovarian cancer risk, i.e. RRSO at recommended age of 35–40 in BRCA1 and at recommended age of 40–45 in BRCA2 mutation carriers, with an innovative risk-reducing strategy." (PMID 26286255, 2015). "In this study, therefore, we performed next-generation sequencing (NGS) analysis of the entire coding regions of BRCA1 and BRCA2 in 135 breast and/or ovarian cancer patients." (PMID 25802882, 2015). "This relative heterogeneity of ovarian cancer beyondBRCA1 and BRCA2 makes it ideally suited to either paneltesting or exome testing, whereby comprehensive testing of multiple genes inparallel is performed." (PMID 26669451, 2015).
ovarian carcinoma (continued). "These were identified through genome-wide association studies (GWAS) of breast or ovarian cancer in the general population or through BRCA1- and BRCA2-specific GWAS." (PMID 24698998, 2014). "Ovarian cancer (OC) mostly arises sporadically, but a fraction of cases are associated with mutations in BRCA1 and BRCA2 genes." (PMID 25136623, 2014). "In particular, inherited mutations in the HR mediators BRCA1 and BRCA2 are associated with increased risk of breast and ovarian cancer, and BRCA-mutated ovarian cancers show distinct therapeutic responses." (PMID 24829461, 2014). "Introduction of Aur A and/or B shRNAs into cells along with BRCA1 or/and BRCA2 shRNAs in both pancreatic and ovarian cancer cells evidently reduced the number of colonies, compared with in cells expressing BRCA1 or/and BRCA2 shRNAs only." (PMID 24775809, 2014). "We found that, not only BRCA2 mutation carriers, but also BRCA1 mutation carriers had significantly improved survival than wild-type ovarian cancer patients." (PMID 25437005, 2014). "Carriers of BRCA mutations are at increased risk of both breast and ovarian cancer; such risks are consistently estimated to be higher in BRCA1 than in BRCA2 mutation carriers; moreover, the risk is higher for breast than for OC." (PMID 25136623, 2014). "Much of the current research surrounds the use of PARP inhibitors as effective mono-therapy for breast and ovarian cancers with BRCA1 and BRCA2 mutations." (PMID 25369795, 2014). "Lastly, exon 11 of BRCA2, another important genetic determinant for hereditary breast and ovarian cancers, was also sequenced from diverse primate species." (PMID 25011685, 2014). "Because of the rapidly evolving nature of BRCA1, we also completed an evolutionary analysis of BRCA2, another strong determinant for hereditary breast and ovarian cancer." (PMID 25011685, 2014). "Germline mutations in at least four Fanconi Anemia genes (BRCA2, PALB2, RAD51C, BRIP1) have thus far been found to contribute to the inherited risk of breast or ovarian cancer." (PMID 24465539, 2014). "In more than 70% of families with a strong history of breast and ovarian cancers, pathogenic mutation in BRCA1 or BRCA2 cannot be identified, even though hereditary factors are expected to be involved." (PMID 24479546, 2014). "Our unpublished data show that Dinaciclib exposure results in downregulation of BRCA1 and BRCA2 and sensitized cyclin E1-dependent ovarian cancer cells to cisplatin." (PMID 24624361, 2014). "Skewed activation in women with breast and ovarian cancers, at least in part, has been attributed to BRCA1 and to a lesser extend BRCA2 mutations." (PMID 25036526, 2014). "We review the molecular signaling pathways that converge on BRCA1 and BRCA2, their activation status in ovarian cancer, and therapeutic options to modulate BRCA function." (PMID 24624361, 2014). "The lifetime risk of developing ovarian cancer is estimated to be 54% and 23% for carriers of BRCA1 and BRCA2 mutations, respectively." (PMID 23528888, 2013). "Moreover, multiple genetic and epigenetic mechanisms cause the inactivation of BRCA1, BRCA2, and/or other repair factors in hereditary and sporadic ovarian cancer, and it was estimated that as much as 50% of epithelial ovarian cancer could be homologous recombination deficient." (PMID 23344037, 2013). "As with BRCA2/FancD1, BRIP1/FancJ, and PALB2/FancN, bi-allelic mutations in RAD51C/FancO cause FA, and mono-allelic mutations increase the risk of breast and ovarian cancer." (PMID 23344037, 2013).
ovarian carcinoma (continued). "This pathway dominates among epithelial ovarian cancers and is further promoted in BRCA1- and BRCA2-mutated tumors, thus necessitating major research efforts to improve diagnosis, as early detection is of utmost importance for therapeutic success." (PMID 23344037, 2013). "A significant association between the total number of somatic exome mutations per genome (Nmut) and patient outcomes was observed in patients whose ovarian cancers possessed mutations in BRCA1 and BRCA2." (PMID 24265793, 2013). "A Canadian study of 1342 ovarian cancer cases revealed a combined mutation frequency of 13.3% of both BRCA1 and BRCA2, 8% of which was BRCA1." (PMID 23536787, 2013). "Taken together, BRCA1 and BRCA2 appear to play critical roles in development of ovarian cancer and modulation of chemotherapy responsiveness." (PMID 23964347, 2013). "Associations with SNPs at the novel 17q21 region with ovarian cancer risk for BRCA1 and BRCA2 mutation carriers." (PMID 23544013, 2013). "Both preclinical and clinical data suggest that alterations in BRCA1 or BRCA2 have prognostic value in ovarian cancer." (PMID 23964347, 2013). "Previous studies of the known common ovarian cancer susceptibility alleles found significant associations with ovarian cancer for both BRCA1 and BRCA2 carriers." (PMID 23544013, 2013). "Two (0.6%) PALB2 mutation carriers were reported in a study of 360 ovarian cancer cases that were also screened for BRCA1, BRCA2 and other recently described cancer susceptibility genes." (PMID 23302520, 2013). "Most ovarian cancers are due to sporadic events and 8–10% are attributable primarily to germline mutations in breast cancer 1 (BRCA1) or BRCA2 genes." (PMID 23964347, 2013). "Specific BRCA mutations can confer a different risk of disease, consistent to the fact that breast and ovarian cancer are multifactorial diseases, which can be influenced by many environmental and/or genetic factors affecting BRCA1 or BRCA2 penetrance." (PMID 23354980, 2013). "Ovarian cancers carrying BRCA1 and BRCA2 mutations (mBRCA) display massive chromosomal alterations, and are more sensitive to DNA cross-linking agents containing platinum, and to PARP inhibitors." (PMID 24265793, 2013). "Although new predisposing genes have been identified lately, the important players to ovarian cancer susceptibility are still the known BRCA1 and BRCA2 genes." (PMID 23536787, 2013). "For ovarian cancer data, we used both sequencing and copy number data and found that BRCA1 and BRCA2 increase the rate of point mutations and the chromosomal regions 8p21.2 and 22q13.33 increase the rate of copy number alterations." (PMID 24330428, 2013). "The presence of Spanish family who suffered from ovarian cancer and early onset ovarian cancer or BC is a major clue for the screening of BRCA1 and BRCA2 gene mutations." (PMID 24312913, 2013). "The present study sought to correlate whole-exome mutation burden in tumor tissue (Nmut) to treatment outcome in ovarian cancer patients, and to examine this relationship in patients with BRCA1 and BRCA2 mutations in their ovarian tumors." (PMID 24265793, 2013). "Several correlated SNPs at 17q21.31 from the iCOGS array provided strong evidence of association with ovarian cancer risk in both BRCA1 and BRCA2 mutation carriers." (PMID 23544013, 2013). "After BRCA2/FancD1, two other genes, namely, BRIP1/FancJ and PALB2/FancN, were described as FA and breast and ovarian cancer susceptibility genes, suggesting a strong genetic connection between FA and hereditary breast and ovarian cancer." (PMID 23344037, 2013). "In terms of histological features, ovarian cancer from both BRCA1 and BRCA2 mutation carriers were found to predominantly belong to the high-grade serous carcinoma subtype." (PMID 23344037, 2013).